CYP1A1 (cytochrome P450 family 1 subfamily A member 1)
Diseases named in the same sentence as CYP1A1 in open-access papers (continued):
Sharing a sentence is not in itself a finding about the gene and the disease.
cervical carcinoma (continued). "In the three effect model, SNP rs1048943 (CYP1A1 G/A) all demonstrated the highly significant association with cervical cancer (All p values < 0.00001)." (PMID 25928231, 2015). "The biological significance of variant CYP1A1*2A variant allele is uncertain, but CYP1A1*2A has been reported to increase susceptibility to several cancer types, including lung, breast, and cervical cancer." (PMID 25654087, 2015). "rs1048943 (CYP1A1) also showed the strongest association with cervical cancer in the dominant effect model (OR = 0.40, 95% CI [0.25, 0.66])." (PMID 25928231, 2015). "Patients A and B were active smokers, a known risk factor for cervical cancer that may enhance the carcinogenic effects of HPV through CYP1A1-mediated metabolism of tobacco-derived xenobiotics." (PMID 40433454, 2025). "Host genetic predisposition in the CYP1A1 may be associated with an increased susceptibility to cervical cancer.The study aimed to evaluate four common polymorphisms of the CYP1A1 and cervical cancer susceptibility among Northeast Thai women." (PMID 31983191, 2020). "Although most of them indicated that CYP1A1 Ile462Val polymorphism might be a risk factor for cervical cancer, the effects of the polymorphism on different ethnic groups were not fully clarified." (PMID 29326607, 2017). "Therefore, we conducted this cumulative meta-analysis to obtain accurate and up-to-date estimates of the association between the CYP1A1 Ile462Val polymorphism and cervical cancer susceptibility." (PMID 29326607, 2017). "In total analysis, the association between CYP1A1 Ile462Val polymorphism and cervical cancer incidence is borderline and may indicate a role of this variant." (PMID 29326607, 2017). "Hence, we performed this updated and cumulative meta-analysis to ascertain a more accurate association between CYP1A1 Ile462Val polymorphism and risk of cervical cancer." (PMID 29326607, 2017). "Thus, we identified relevant published reports through a systematic search strategy, and performed this updated and cumulative meta-analysis to reappraise between CYP1A1 Ile462Val polymorphism and risk of cervical cancer." (PMID 29326607, 2017). "It provides an important theoretical basis to reveal the CYP1A1 Ile462Val polymorphism and the biological mechanism of developing cervical cancer, which may be helpful to predict the occurrence of cervical cancer in Caucasian females." (PMID 29326607, 2017). "Indeed, we observed significant differences in distribution of CYP1A1 allelic frequencies (p = 0.002), where the allele C is a risk for cervical cancer." (PMID 26798414, 2016). "Indeed, the allele C of CYP1A1 features associated to risk for cervical cancer, which contributes to a higher activity expression of the enzyme." (PMID 26798414, 2016). "We also observed that the CYP1A1&COMT TC&HH might increase the risk for cervical cancer, though with a wide confidence interval (OR = 13.67, 95% CI = 1.72–109.39, p = 0.014) (data not shown)." (PMID 26798414, 2016). "Significant association of CYP1A1 m2 (rs1048943) polymorphism with platinum drugs (e.g. Cisplatin) was observed, which represent an important class of anticancer agents and are frequently used in treatment of various types of solid cancers including cervical cancer." (PMID 35996502, 2022). "Moreover, none of the previous studies have documented any association between m4 polymorphisms and cervical cancer; notwithstanding, our finding that the A allele existed only among cases (p<0.0001) strongly suggests participation of the CYP1A1 m4 A allele in the development of cervical cancer." (PMID 31983191, 2020). "Because the enzymes COMT and CYP1A1 are closely related and work in metabolic sequence in the metabolism of estrogens, it is important to examine if the functional polymorphisms of these enzymes in association change the risk to develop cervical cancer in the carriers." (PMID 26798414, 2016).
cervical carcinoma (continued). "There is a significant correlation between CYP1A1 and the infiltration level of T cells in cervical cancer." (PMID 39206151, 2024). "There is at least one study able to associate CYP1A1 with susceptibility to HPV infection, and all of our variants (T5639C, A4889G, and C4887A) were found to be involved in cervical cancer in other studies." (PMID 37891885, 2023). "The expression of AHR and CYP1A1 were analyzed by immunohistochemistry in 30 normal cervical tissue samples and 30 cervical cancer tissue samples." (PMID 34784845, 2021). "Compared with the normal cervical group, AHR and CYP1A1 are widely expressed in cervical cancer tissues." (PMID 34784845, 2021). "We performed the determination of CYP1A1 (rs4646903) and COMT (rs4680) polymorphisms in 130 women with cervical cancer and 180 healthy women." (PMID 26798414, 2016). "We observed that the genotypes for CYP1A1 and COMT for intermediate activity represented the highest risk for developing cervical cancer of that observed individually for COMT genotype that was protector." (PMID 26798414, 2016). "We studied the association of CYP1A1 M1 (rs4646903) and COMT (rs4680) polymorphisms in 130 cervical cancer cases (c-cancer) and 179 controls." (PMID 26798414, 2016). "This is the first study in Portugal that exposes the interaction of CYP1A1 and COMT polymorphisms in cervical cancer." (PMID 26798414, 2016). "According with the following model as CYP1A1 TC&CC and CYP1A1 TT genotypes separately, we observed significant higher values of estradiol in cervical cancer (p > 0.001)." (PMID 26798414, 2016). "In contrast to HepG2 hepatocarcinoma cells, HeLa cervical carcinoma cells showed significantly lower levels of CYP1A1 mRNA expression following PCB 126 exposure." (PMID 25116688, 2014). "In addition, the high expression of CYP1A1 and T cells in cervical cancer is unfavorable for the prognosis of cervical cancer patients." (PMID 39206151, 2024). "Association of genotypes of CYP1A1 T>C rs4646903, CYP1A1 A>G rs1048943, CYP2E1 T>A rs6413432, RAD51 G>C rs1801320, XRCC1 G>A rs25487, XRCC2 G>A rs3218536 and XRCC3 C>T rs861539 polymorphisms and survival after treatment (CRT) for cervical cancer." (PMID 35996502, 2022). "Association of genotypes of CYP1A1 T>C rs4646903, CYP1A1 A>G rs1048943, CYP2E1 T>A rs6413432, RAD51 G>C rs1801320, XRCC1 G>A, rs25487 XRCC2 G>A rs3218536 and XRCC3 C>T rs861539 polymorphisms with vital status and recurrence of cervical cancer cases (n = 227)." (PMID 35996502, 2022). "Association of genotypes of CYP1A1 T>C rs4646903, CYP1A1 A>G rs1048943, CYP2E1 T>A rs6413432, RAD51 G>C rs1801320, XRCC1 G>A, rs25487 XRCC2 G>A rs3218536 and XRCC3 C>T rs861539 polymorphisms with clinical response of cervical cancer cases (n = 227)." (PMID 35996502, 2022). "IHC results indicated that AHR and CYP1A1 were widely expressed in cervical cancer." (PMID 34784845, 2021). "In addition, Kaplan-Meier plotter showed that high expression of AHR, CYP1A1, HSP90AA1, and HSP90AB1 and low expression of ESR1 were associated with a high hazard ratio for poor overall survival in cervical cancers." (PMID 34784845, 2021). "So far, numerous studies have been conducted on the association between CYP1A1 Ile462Val polymorphism and the susceptibility to cervical cancer, but the conclusions are not unanimous." (PMID 29326607, 2017). "To investigate whether profiles of CYP1A1 and COMT genotypes might be associated with the risk of cervical cancer, we examined the effect combinations of genotypes." (PMID 26798414, 2016). "Interestingly, Gutman and co-workers reported that the CYP1A1 MspI C/C polymorphism is unlikely to be a major risk factor for cervical cancer which is contrary to our data from the meta-analysis." (PMID 24391993, 2013). "High expression of AHR, CYP1A1, HSP90AA1, and HSP90AB1 and low expression of ESR1 were negatively correlated with the prognoses of cervical cancer patients." (PMID 34784845, 2021).
cervical carcinoma (continued). "In this study, we showed that the expression of CYP1A1, AIP, CYP1B1, ESR1, and MAF was significantly correlated with the level of T cell infiltration in cervical cancer." (PMID 34784845, 2021). "In particular, AHR, CYP1A1 and ESR1 were identified as potential prognostic biomarkers and shown to be correlated with immune responses in cervical cancer." (PMID 34784845, 2021). "Our results demonstrated a possible involvement of the CYP1A1 m4 polymorphism but no other common polymorphisms (viz., m1, m2, and m3) in the risk for cervical cancer.This finding may be useful when screening for risk of cervical cancer among Northeast Thai women." (PMID 31983191, 2020). "So, an association study of functional polymorphisms involved in synthesis of 2-methoxy-estradiol, namely, CYP1A1 (rs4646903) and COMT (rs4680), could contribute to understanding the role of estrogen in cervical cancer." (PMID 26798414, 2016). "Moreover, the expression of CYP1A1 was negatively correlated with the level of T cells in cervical cancer, and high expression of CYP1A1 was not conducive to the prognosis of patients with cervical cancer." (PMID 34784845, 2021). "Interestingly, the CA genotype of CYP1A1 m4 was observed in 30.88% of the cervical cancer patients but was absent in healthy controls." (PMID 31983191, 2020). "Generally, high expression of AHR, CYP1A1, HSP90AA1, and HSP90AB1 and low expression of ESR1 were not conducive to the prognosis of cervical cancer patients." (PMID 34784845, 2021).
colitis (18 papers, 2016 to 2026). Inflammation of the colon. "Previously, it was shown that overexpression of CYP1A1 in gut epithelial cells led to decreased AhR ligands (quasi AhR-deficient) and displayed enhanced susceptibility to Citrobacter rodentium-induced colitis." (PMID 36159798, 2022). "Similar to I3C, our data showed that TCDD upregulated AhR, CYP1A1 and mBD‐1 in CECs from control and colitis (anti‐CD40/ DSS‐ induced) animals." (PMID 40410944, 2025). "We assessed AhR activation by measuring the mRNA expression of its target gene, CYP1A1, which was notably reduced in mice with colitis." (PMID 40410944, 2025). "AHR and CYP1A1 were significantly downregulated in DSS-induced colitis mice, whereas they were significantly upregulated by BTW treatment." (PMID 38974042, 2024). "To understand the mechanisms of dietary I3C in protection against colitis, we first evaluated AhR activation by +I3C diet by assessing mRNA levels of the AhR target gene, CYP1A1." (PMID 38068838, 2023). "When glucosinolate-rich cabbage was consumed, the AHR target gene CYP1A1 was substantially upregulated in the colon, which also reduced colitis." (PMID 37179416, 2023). "T-reg cells in mLN were significantly reduced both in WT and Cyp1a1-/- mice that were subjected DSS-induced colitis." (PMID 36159798, 2022). "In the current study, we examined the role of CYP1A1 in UroA-mediated protective activities against colitis." (PMID 36159798, 2022). "To investigate the contribution of CYP1A1 in UroA-mediated gut barrier protective activities against DSS-induced colitis, we have evaluated the gut permeability." (PMID 36159798, 2022). "In support of the decreased cytochrome P450 activity in metabolomic result, we observed that CYP3A4 and CYP1A1 protein abundance was markedly reduced in the colon samples of colitis mice subjected to the CYN therapy." (PMID 36278202, 2022). "Our results suggest that CYP1A1 expression is essential for UroA-mediated enhanced gut barrier functions and protective activities against colitis." (PMID 36159798, 2022). "The enhanced level of CYP1A1 also indicated the activation of AHR in DSS-induced colitis mouse model." (PMID 35935130, 2022). "To determine the role of CYP1A1 in UroA-mediated protectives activities against colitis, we subjected C57BL/6 mice and Cyp1a1-/- mice to dextran sodium sulphate (DSS)-induced acute colitis model." (PMID 36159798, 2022). "Overall, here for the first time, we showed that UroA requires the functional expression of CYP1A1 to exert its physiological activities and mitigation of colitis in pre-clinical models." (PMID 36159798, 2022). "Our current study suggests that CYP1A1 is critical for UroA-mediated regulation of intestinal barrier function, anti-inflammatory activities and mitigation of colitis." (PMID 36159798, 2022). "Here, we explored the role of CYP1A1 in UroA-mediated protective activities against DSS-induced colitis using Cyp1a1-/- mice." (PMID 36159798, 2022). "To explore the pathway by which L-fucose acts on CD4+ T cells and LPMCs, we found that the mRNA levels of AHR and its target gene, CYP1A1, were significantly elevated in the colons of colitis mice by L-fucose treatment." (PMID 36432480, 2022). "In summary, we showed that UroA-mediated protective activities against colitis dependent upon expression of CYP1A1 in addition to AhR." (PMID 36159798, 2022). "While AHR and its target gene CYP1A1 were increased after L-fucose administration in DSS-induced colitis." (PMID 36432480, 2022). "Interestingly, we observed that very mild reduction of permeability in Cyp1a1-/- mice (colitis mice) upon treatment of UroA compared to WT mice." (PMID 36159798, 2022). "However, the direct role of CYP1A1 beyond drug metabolism and its role in intestinal disorders such as in colitis are yet to be explored." (PMID 36159798, 2022). "Cell-specific deletion of AhR and CYP1A1 may provide better understanding of how UroA-mediated activities regulate differentially to mitigate colitis." (PMID 36159798, 2022).
colitis (continued). "Only the mRNA expression of Cyp1a1 in liver samples of the mice pre-treated by a 2 week administration of SB prior to DSS (group 4) has shown a significant increase compared to group 5 with DSS-induced colitis." (PMID 35928257, 2022). "Here, we asked whether AhR downstream inducer, CYP1A1 is required for UroA-mediated functional activities to protect against colitis." (PMID 36159798, 2022). "In addition, alpinetin (15, 30 mg/kg) obviously increased the mRNA and protein expressions of AhR target gene CYP1A1 in colons of colitis mice." (PMID 30166541, 2018). "However, UroA-failed to protect Cyp1a1-/- mice against colitis, as evident from non-recovery of body weight loss, shortened colon lengths and colon weight/length ratios." (PMID 36159798, 2022). "High indole-3-lactic acid (ILA) production is a key tryptophan metabolic characteristic of L. plantarum which activated AHR downstream signaling (such as CYP1A1, IL-22, and STAT3) to alleviate colitis." (PMID 41019044, 2025). "Lactobacillus bulgaricus strain OLL1181 alleviated DSS-colitis by activating AHR signaling and increasing the expression of CYP1A1." (PMID 37179416, 2023). "β-naphthoflavone (β-NF) is a high-affinity synthetic AhR ligand that is a CYP1A1 substrate and has also been shown to decrease the severity of DSS-colitis." (PMID 32017483, 2020). "Furthermore, administration of myricet in significantly increased the relative expressions of CYP1A1 and CYP1B1, whereas AhR inhibitor abolished the amelioration of myricetin on DSS-induced colitis." (PMID 39974840, 2025). "Treatment with UroA restored the DC population in WT mice but not in Cyp1a1-/- mice that were subjected to DSS-induced colitis." (PMID 36159798, 2022). "To investigate whether UroA changes the DSS-induced inflammatory immune cell balance in CYP1A1 dependent manner, we profiled the immune cells from mesenteric lymph node (mLN) of DSS-induced colitis mice, and compared with control and UroA treated mice." (PMID 36159798, 2022). "A recent study indicated that the aromatic compounds in coffee could promote the expression of CYP1A1 and CYP1B1 by activating AhR, which alleviates experimental colitis." (PMID 36145261, 2022). "Our results suggested that the treatment with UroA protected the WT mice, but not Cyp1a1-/- mice from DSS-induced colitis." (PMID 36159798, 2022). "Treatment with UroA significantly reduced/restored CD4+ T cell population in WT mice, but not in Cyp1a1-/- mice suggesting critical role of CYP1A1 in UroA-mediated correction of immune abnormalities in colitis." (PMID 36159798, 2022). "Mechanistically, inhibitor CH223191 markedly down-regulated the mRNA and protein levels of AhR and its downstream targets CYP1A1 and IL22 in colonic tissue compared with HQD treatment alone, underscoring the critical role of AhR activation in HQD-mediated alleviation of experimental colitis." (PMID 41530817, 2026). "Importantly, treatment with UroA reversed or restored the mucin levels in WT colitis (DSS+UroA) mice but not in Cyp1a1-/- mice." (PMID 36159798, 2022). "Thus far, the requirement of basal level of CYP1A1 for AhR-mediated protective activities against colitis has not been reported." (PMID 36159798, 2022). "However, UroA treatment failed to block the increased MPO levels in Cyp1a1-/- mice that were subjected DSS-induced colitis model." (PMID 36159798, 2022). "It is possible that the accumulation of AhR ligands in Cyp1a1-/- mice may not be at the same levels compared to triple Cyp knockout mice (lack of CYP1A1, CYP1A2 and CYP1B1 enzymes) to render the beneficial activities against DSS-induced colitis." (PMID 36159798, 2022).